BNIP3 (BCL2 interacting protein 3)
Diseases named in the same sentence as BNIP3 in open-access papers (continued):
Sharing a sentence is not in itself a finding about the gene and the disease.
lung cancer (continued). "BNIP3 is frequently overexpressed during different stages of lung cancer and high BNIP3 expression was described as a major independent factor for overall NSCLC patients’ survival." (PMID 33207677, 2020). "In this review, we shed light on the BNIP3‘s role in different types of cancer in general and lung cancer, in particular, as well as suggested its potential for targeting therapy of lung cancer." (PMID 33207677, 2020). "In lung cancer cell line A549, cisplatin‐based combination treatment triggered cell death by induction of BNIP3." (PMID 32412667, 2020). "Although potential involvement of BNIP3 in cancer progression has been discussed in many review articles, its specific role in lung cancer is still unclear." (PMID 33207677, 2020). "In vitro experiments also confirmed that BNIP3 participated in lung cancer cell migration by interacting with aryl hydrocarbon receptor (AhR)." (PMID 31938577, 2020). "Contradictions in the prognostic role of BNIP3 in different stages of lung cancer can be explained by the ambiguous action of autophagy and mitophagy, including those regulated by BNIP3." (PMID 33207677, 2020). "In this study, lung cancer cells were treated with a chemotherapy drug alone or in combination to identify the role of BNIP3 and autophagy in combination chemotherapy for treating cancer." (PMID 31856355, 2020). "Herein, we investigated the degradation pathway of BNIP3 in an immunoprecipitation assay to evaluate the relationship between AhR and BNIP3 during autophagy in lung cancer." (PMID 28195146, 2017). "In conclusion, the present study demonstrated that cisplatin resistance in lung cancer cells under hypoxia can be explained by the augmented induction of autophagy, which suppressed BNIP3 death pathway." (PMID 26201611, 2015). "Cyclovirobuxine D (CVB-D)-induced mitophagy is regulated via p65/BNIP3/LC3 axis in lung cancer." (PMID 36831455, 2023). "BNIP3 overexpression has also been shown to enhance tumor growth for lung cancer and liver cancer." (PMID 35912211, 2022). "BNIP3-positive cancer cell subpopulation was also detected in lung cancer." (PMID 35912211, 2022). "Moreover, research suggested that the elevated BNIP3 levels were correlated with progression to metastasis and poor prognosis in multiple cancers, such as breast and lung cancers, and uveal melanoma." (PMID 34335109, 2021). "Similarly, high expression of BNIP3 is detected in 70% of patients with lung cancer subtypes, such as lung AD and SCC." (PMID 33207677, 2020). "Previous studies also reported cisplatin‐induced BNIP3 up‐regulation in lung cancer cell line A549." (PMID 32412667, 2020). "In the later stages of lung cancer, isolated cell populations are formed, in which autophagy and mitophagy function simultaneously as factors for enhancing cell survival and death, thus leveling the prognostic role of BNIP3." (PMID 33207677, 2020). "As our present data showed that autophagy helps lung cancer cells survive chemo drug treatment, we wanted to determine whether inhibition of autophagy can enhance BNIP3‐mediated cell response to the cytotoxic effect of chemo drugs." (PMID 31856355, 2020). "MAC and CoCl2 upregulated LC3‐II, Beclin1, ATG7, and BNIP3 in the different lung cancer cells." (PMID 30338933, 2018). "Taken together, we found that AhR regulates BNIP3 degradation to disturb the autophagy process in lung cancer cells, which may result in decreased cellular EMT." (PMID 28195146, 2017). "Revealing of new BNIP3 mechanisms of action and its potential link to oncogenesis signaling could result in considering BNIP3 as an attractive candidate for targeted therapy of lung cancer in the near future." (PMID 33207677, 2020). "Therefore, in addition to chemotherapeutic drugs, a combination of BNIP3 activation and autophagy inhibition may be a better strategy for lung cancer therapy." (PMID 31856355, 2020).
lung cancer (continued). "We found that BNIP3 and ROS may be involved in combination chemo drug‐induced cell death and inhibition of autophagy to improve the effects of combination chemotherapy in treating lung cancer." (PMID 31856355, 2020). "Next, a lung cancer dataset with 42 patients was integrated with CCA or harmony algorithm and employed to obtain BNIP3 altered gene lists and pathways." (PMID 35912211, 2022). "We detected a significant elevation of BNIP3 and BNIP3L expression in lung cancer cells in a dose-dependent manner upon CVB-D treatment." (PMID 34072333, 2021). "BNIP3 is a crucial player in autophagy, apoptosis and EMT processes in cancer, in general, and in lung cancer, in particular." (PMID 33207677, 2020). "Therefore, BNIP3 might act as a link between lung cancer cell death and its dissemination." (PMID 33207677, 2020). "MS-MLPA allowed identification of a number of new and possibly interesting epigenetic alterations such as HLTF, ID4, BNIP3, H2AFX, CACNA1G, CACNA1A and TGIF genes, serving to gain more insight into the development of lung carcinomas." (PMID 20849603, 2010). "To explore whether p65 inhibition is a potential factor in mediating BNIP3 upregulation in CVB-D-treated lung cancer cells, we established p65 overexpression and knockdown cells to explore its roles in CVB-D-induced BNIP3 upregulation." (PMID 34072333, 2021). "The FUZ-BNIP3 axis may be considered as one of a potential group involving FUZ and BNIP3 as highly expressed proteins and FUZ as a prognostic factor of overall survival in patients with lung cancer." (PMID 33207677, 2020). "Despite the high frequency of BNIP3 overexpression in tumor specimens, according to 5-year survival, BNIP3 is not correlated with survival probability in patients with different stages of lung cancer and its subtypes, including lung AD and SCC." (PMID 33207677, 2020). "Importantly, our study identified seven novel methylated candidates in lung cancer, including HLTF, ID4, BNIP3, H2AFX, CACNA1G, CACNA1A and TGIF." (PMID 20849603, 2010). "Also, BNIP3 was inferred as an independent prognostic factor that related to autophagy in early-stage NSCLC but not clear in advanced lung cancer." (PMID 36092153, 2022). "Hence, BNIP3 might be a link between the pathway of endogenous compounds metabolism and metastasis-related EMT of lung cancer cells." (PMID 33207677, 2020). "Knocking down BNIP3 with transfection reagent, then we extracted proteins and detected GSDMD and caspase-8 by western blot, and the results showed that knocking down BNIP3 increased GSDMD and caspase-8, indicating that knocking down BNIP3 could induce pyroptosis in lung cancer cells H358." (PMID 36092153, 2022).
colorectal cancer (22 papers, 2008 to 2024). A primary or metastatic malignant neoplasm that affects the colon or rectum. "Increased resistance to hypoxia-induced cell death of pancreatic and colorectal cancer cells deficient for Bnip3 further supports the relevance of Bnip3 during hypoxia-induced death." (PMID 21437288, 2011). "Moreover, scientific evidence has confirmed a close association between BNIP3 silencing and chemoresistance acquisition to 5-FU and oxaliplatin in colorectal cancer, and to gemcitabine and 5-FU in pancreatic ductal adenocarcinoma." (PMID 31835431, 2019). "BNIP3 is inactivated by methylation of the CpG island at the transcriptional start site in gastric, pancreatic, and colorectal cancer, and methylase inhibitor 5-aza deoxycytidine can restore the deficiency." (PMID 36675706, 2022). "On the other hand, decreased levels of BNIP3 mRNA and protein were found in pancreatic and colorectal cancer, hematopoietic malignancies and hepatocellular carcinoma (HCC)." (PMID 33207677, 2020). "This phenomenon has been largely studied in colorectal cancer, where 5-Aza recovered BNIP3 expression as a biosensitizer pretreatment of irinotecan and to increase chemosensitivity to 5-FU in colorectal cancer." (PMID 31835431, 2019). "In pancreatic adenocarcinoma and colorectal cancer Bnip3 transcription is prevented by hypermethylation of the Bnip3 promoter." (PMID 24811485, 2014). "FTO is a m6A demethylase that promotes breast tumor progression by inhibiting BNIP3, whereas another study reported inhibitory effect of FTO on metastasis by targeting demethylating metastasis-associated protein 1 (MTA1) mRNA in colorectal cancer." (PMID 35090515, 2022). "The inactivation of BNIP3 likely plays a vital role in the progression of colorectal cancer and GC." (PMID 33428603, 2021). "Likewise, silencing of the BNIP3 gene through aberrant methylation was correlated with resistance to therapy in colorectal cancer." (PMID 33207677, 2020). "Thus, the BNIP3 promoter is methylated in colorectal carcinoma, pancreas adenocarcinoma, several types of hematopoietic tumors and BNIP3 re-expression by methyltransferase inhibitor restored hypoxia-inducible cell death." (PMID 33207677, 2020). "Additionally, BNIP3 upregulation in a DNA demethylation-dependent manner in colorectal cancer has been reported to overcome apoptosis resistance after verticillin A treatment and related to DNMT1 inhibition following radiotherapy and chemotherapy." (PMID 31835431, 2019). "However, the BNIP3 promoter was methylated in two colorectal cancer cell lines (SW480 and LoVo), suggesting that the BNIP3 gene is inactivated in colorectal cancer." (PMID 26727575, 2016). "As almost half of the 57 colorectal cancer patients enrolled in the present study exhibited BNIP3 promoter methylation, we speculate that inactivation of the BNIP3 gene may occur during the early stage of colon cancer development." (PMID 26727575, 2016).
colorectal cancer (continued). "Hypermethylation of five autophagy-related genes, BECN-1, ATG16L2, ULK2, BNIP3 and a variant of LC3A, were previously reported respectively in BC, leukemia, astrocytoma, colorectal cancer and esophageal carcinoma and these data demonstrated that this hypermethylation was correlated to tumor grade." (PMID 26474850, 2015). "This is particularly the case in oncology, where it is observed that in some cancers, such as pancreatic, gastric, and colorectal cancers, BNIP3 expression is suppressed or silenced by DNA methylation, suggesting that the cells have blocked BNIP3 expression to evade cell death." (PMID 26102349, 2015). "The role of BNIP3 in colorectal cancer (CRC) is unknown, although 66% tumours show BNIP3 silencing by promoter hypermethylation." (PMID 18728663, 2008). "However, given that the silencing and downregulation of the BNIP3 gene has been observed in gastric and colorectal cancers, as 5′ CpG island DNA methylation occurs frequently, the inactivation of BNIP3 is considered to play an important role in gastrointestinal cancer progression." (PMID 38473345, 2024). "Increased mitochondrial oxidative stress by radiation induced BNIP3- and BNIP3L-mediated mitophagy to protect colorectal cancer cells from radiation-induced cytotoxicity." (PMID 36430876, 2022). "To explore the role of the Mieap-regulated mitochondrial quality control pathway in colorectal cancer, we examined the promoter-methylation status of the Mieap, BNIP3 and NIX genes in primary cancer and corresponded normal tissues of 57 colorectal cancer patients by performing MSP." (PMID 26727575, 2016). "In this study, we undertook a retrospective observational analysis of tissue-banked tumor and paired normal tissue from 49 colorectal cancer patients, measuring ascorbate levels, HIF-1α and its downstream gene products BNIP3, and vascular endothelial cell growth factor (VEGF)." (PMID 24551593, 2014). "Besides, other authors have evidenced knockdown of BNIP3 in colorectal cancer cells by both methylation of its 5′ CpG island and deacetylation of histone in that region, showing that 5-Aza and TSA administration recovered BNIP3 expression, even better in combination." (PMID 31835431, 2019).
myocardial ischemia (22 papers, 2009 to 2026). A disorder of cardiac function caused by insufficient blood flow to the muscle tissue of the heart. "Consistent with our results, a study focusing on myocardial ischemia reperfusion, found that high BNIP3 levels cause p62 accumulation." (PMID 32190178, 2020). "Studies have demonstrated that BNIP3 has been critically implicated in the pathogenesis of cardiac ischemia." (PMID 23691217, 2013). "BNIP3 has various cellular functions and has also been shown to be involved in various disease conditions, including myocardial ischemia, autophagy, and apoptosis, and is thereby associated with the pathogenesis of diseases such as cardiovascular disease and cancer." (PMID 39728572, 2024). "For instance, BNIP3-mediated mitophagy has been shown to protect cardiomyocytes during myocardial ischemia/reperfusion injury." (PMID 40423411, 2025). "Deficiency of the autophagy protein receptor B-cell leukemia/lymphoma 2 protein (BCL2) interacting protein 3 (Bnip3) in mice reduced myocardial damage and preserved the heart structure following cardiac ischemia/reperfusion injury." (PMID 37175915, 2023). "Reportedly, mitophagy induced by the BNIP3 signaling pathway can produce a protective effect during myocardial ischemia." (PMID 35187131, 2022). "Autophagy induced by HIF-1α/BNIP3 signaling pathway plays a protective role in myocardial ischemia-reperfusion injury." (PMID 36187470, 2022). "Berberine mediates BNIP3 expression by enhancing the binding of HIF-1α to the BNIP3 promoter, thereby inducing cardiomyocyte proliferation and autophagosome formation to inhibit cardiomyocyte apoptosis and myocardial ischemia/reperfusion injury." (PMID 36187470, 2022). "There is evidence that Panax Notoginseng saponins can individually regulate apoptosis and mitochondrial autophagy by the PI3K/Akt and HIF-1α/BNIP3 pathways to protect rat heart from myocardial ischemia and its reperfusion injury." (PMID 34012683, 2021). "Regulated by HIF-1α, BNIP3 changes the mitochondrial permeability, and promotes mitochondrial autophagy ultimately during myocardial ischemia-reperfusion injury." (PMID 32140105, 2020). "HIF-1α/BNIP3 signaling pathway-induced-autophagy plays protective role during myocardial ischemia-reperfusion injury." (PMID 33013381, 2020). "And in the case of myocardial ischemia–reperfusion injury, BNIP3 also activates mitophagy to clear damaged mitochondria." (PMID 32912324, 2020). "Deferoxamine treatment combined with sevoflurane postconditioning improves myocardial ischemia reperfusion injury by regulating HIF-1/BNIP3-mediated mitophagy in diabetic rats." (PMID 32912324, 2020). "The results indicate that HIF-1/BNIP3-mediated mitochondrial autophagy is involved in SPostC against myocardial ischemia-reperfusion injury." (PMID 32140105, 2020). "In a model of myocardial ischemia and reperfusion, Bnip3 was reported as a mitochondrial sensor of oxidative stress, thus contributing to cell death during I/R in ex vivo-perfused hearts and in cell culture." (PMID 19862336, 2009). "Furthermore, the HIF-1α/BNIP3-mediated regulation of mitophagy that we have discovered provides new insights into potential therapeutic targets for myocardial ischemia–reperfusion injury." (PMID 38539069, 2024). "Therefore, the HIF-1α/BNIP3 signaling pathway can protect the myocardial ischemia-reperfusion injury by inducing autophagy." (PMID 35586047, 2022). "In cardiomyocytes, the pathological mechanism involved in NIX is mainly related to cardiomyocyte hypertrophy and regulated by Gαq-dependent signaling, while BNIP3 is significantly induced by hypoxia in addition to a combination of hypoxia and acidosis under prolonged myocardial ischemia." (PMID 34211627, 2021). "Therefore, BNIP3/NIX exhibited dual properties during myocardial ischemia/reperfusion injury, inducing cell death and participating in mitophagy process." (PMID 34211627, 2021).
myocardial ischemia (continued). "For instance, in animal models of cardiac ischemia-induced myocardial infarction, BNIP3 induction in ventricular myocytes occurred during early cardiac ischemia and persisted throughout reperfusion in an accompany with mitochondrial dysfunction and cardiomyocyte death." (PMID 31515472, 2019). "The results showed that myocardial ischemia increased the expression of HIF-1 α and activated BNIP3, which subsequently triggered mitochondrial-dependent autophagy." (PMID 35187131, 2022). "Taken together, DFO treatment combined with SPostC could alleviate myocardial ischemia reperfusion injury in diabetic rats by restoring and promoting HIF-1/BNIP3-mediated mitochondrial autophagy." (PMID 32140105, 2020).